CASP2 (caspase 2)
Diseases named in the same sentence as CASP2 in open-access papers (continued):
Sharing a sentence is not in itself a finding about the gene and the disease.
colon carcinoma (continued). "Previously, we reported the constitutive binding of HuR to the 5ʹUTR thereby suppressing caspase-2 translation in colon carcinoma cells." (PMID 29719611, 2018). "Here, we investigated the mechanisms of caspase-2 suppression by HuR and its contribution to chemotherapeutic drug resistance of colon carcinoma cells." (PMID 29719611, 2018). "Coincidentally, transient knockdown of HuR by siRNA can impair clonogenic colon carcinoma cell survival upon ionizing irradiation by an upregulation of caspase-2 translation." (PMID 29719611, 2018). "Recently, we reported that silencing of the the RNA-binding protein HuR in colon carcinoma cells increases the sensitivity of colorectal carcinoma cells to ionizing radiation-induced cell death via the upregulation of caspase-2." (PMID 29719611, 2018). "Our results indicate that colon carcinoma cells upon chemotherapeutic drug exposure induce HuR-dependent caspase-2 repression as a part of a so far unrecognized cell survival program by HuR." (PMID 29719611, 2018). "Saikosaponin a (SSa), a bioactive phytochemical from Bupleurum, triggers sequential caspase-2 and caspase-8 activation, and thereby induces caspase-mediated apoptosis in human colon carcinoma (HCC) cells." (PMID 29245990, 2017). "Overall, our data suggest a model in which SSa induces colon cancer cell apoptosis via caspase-4 activation, followed by DNA damage and/or sequential activation of caspase-2, -8, and -3." (PMID 29245990, 2017). "In our study, we observed for the first time that Casp2 was downregulated in clinical colon cancer tissues." (PMID 26962687, 2016). "It has been reported that caspase-2 is necessary for optimal TRAIL-mediated cleavage of Bid in human colon cancer cells." (PMID 26000607, 2015). "Note that activation of caspase-2 has been reported to activate caspase-8, and sequential activation of caspase-2 and -8 is essential for saikosaponin a-induced apoptosis in human colon cancer cells." (PMID 25227113, 2014). "Additionally, it has been described that caspase-2 and -8 can trigger cell death through a Bax/Bak-independent mechanism in colon cancer cells treated with resveratrol." (PMID 40723174, 2025). "Furthermore, SS-a was found to activate the expression of apoptosis-inducing proteins, including caspase-4, caspase-2, caspase-8, and caspase-3, in colon cancer cells." (PMID 41011202, 2025). "Consistent with the idea that caspase-2 can kill aneuploid cells, loss of caspase-2 in HCT116 colon cancer cells provided partial protection from cell death induced by the aneuploidy-inducing reagent reversine, an inhibitor of MPS1 kinase, crucial for SAC activity." (PMID 39475598, 2024). "However, our results in colon cancer cells for the first time establish activation of caspase-2 and cleavage of Bid as two key events during AURK inhibitor–ABT-737-induced apoptosis." (PMID 36621626, 2023). "In addition to elevations in IAP proteins, we previously identified direct inhibition of caspase-2 translation by the ubiquitous mRNA-binding protein human antigen R (HuR) as a novel path of therapy resistance in colon carcinoma cells." (PMID 31842382, 2019). "Interestingly, the upregulation of caspase-2 upon TRIM25 silencing alone is unable to trigger apoptosis in colon carcinoma cells but requires an additional apoptosis-inducible stimulus, such as doxorubicin." (PMID 31842382, 2019). "In addition, a recent publication demonstrated that transcription of caspase-2 mRNA in colon carcinoma cells is controlled by B-cell CLL/lymphoma 9 protein (BCL9L)." (PMID 31366165, 2019).
colon carcinoma (continued). "Thereby, caspase-2 is able to sensitize colon carcinoma and other human cancer cell lines to γ-irradiation-induced apoptosis primarily through an evolutionarily highly conserved process which is distinct from mitochondrial and death-receptor-triggered cell death pathways." (PMID 31366165, 2019). "In the next set of experiments, we asked for the underlying mechanisms how both chemotherapeutic drugs could activate HuR triggered caspase-2 inhibition in colon carcinoma cells." (PMID 29719611, 2018). "From these data it is tempting to speculate that colon carcinoma cells have evolved mechanisms which counterregulate an increase in caspase-2 levels either via an inhibition of caspase-2 translation and/or via an increased degradation of the enzyme." (PMID 29719611, 2018). "Collectively, these results demonstrate that sensitiziation of colon cancer cells to chemotherapeutic drug-induced cell death by HuR knockdown critically depends on caspase-2 which further propagates the intrinsic apoptotic pathway induced by chemotherapeutic agents." (PMID 29719611, 2018). "Also, we find miR-125a-5p is an oncogene in colon cancer, and identified Casp2 is a new target of miR-125a-5p." (PMID 26962687, 2016). "In addition, the silencing of miR-383 promoted apoptosis by elevating caspase-2 expression, indicating that caspase-2 might be involved in the cell death induced by miR-383, at least in colon cancer cells." (PMID 36171196, 2022). "Therefore, it would be intriguing to investigate whether the constitutive PKCδ-induced phosphorylation of HuR in colon carcinoma cells may have a critical impact on HuR binding to IRES located in the 5 ́UTR of caspase-2 as well." (PMID 31366165, 2019). "In colon cancer cells, RES induces caspase-2 activation that subsequently triggers Bax-Bak-dependent and -independent cell death." (PMID 28157696, 2017). "In 80 clinical colon cancer tissues, HOTAIR and miR-125a-5p levels were higher than adjacent tissues, whereas caspase 2 was lower." (PMID 26962687, 2016). "The key finding of our study is that inhibition of caspase-2 by TRIM25 constitutes a so far unrecognized pathway, which may be relevant for the resistance of human colon carcinoma cells to chemotherapy-induced apoptosis." (PMID 31842382, 2019). "Accordingly, data from human colon carcinoma cells revealed that HuR maintains constitutively reduced protein and activity levels of caspase-2 through negative interference with IRES-mediated translation." (PMID 31366165, 2019). "Conversely, activation of caspase-3 cleavage by doxorubicin was not accompanied by a complete caspase-2 cleavage which implicates that in colon carcinoma cells caspase-2 acts upstream of caspase-3." (PMID 29719611, 2018). "The negative caspase-2 regulation by HuR offers a novel therapeutic target for sensitizing colon carcinoma cells to drug-induced apoptosis." (PMID 29719611, 2018). "To evaluate the expression level of HOTAIR, miR-125a-5p and Casp2 in colon cancer cells, we performed quantitative real-time PCR in 80 paired cancerous and adjacent noncancerous tissues of colon cancer patients." (PMID 26962687, 2016). "The constitutive binding of HuR to caspase-2 mRNA which we observed in colon carcinoma cells suggests a stable rather than a transient repression of caspase-2 translation, which is further augmented after exposure of cells with either chemotherapeutic agents or γ-irradiation." (PMID 31366165, 2019). "A caspase-2-dependent increase in paclitaxel-induced caspase-3 cleavage upon siRNA-mediated knockdown of HuR was also found in HCT-15 cells implicating that the sensitization of human colon carcinoma cells to apoptosis by HuR depletion is not a cell-type specific phenomenon." (PMID 29719611, 2018).
colon carcinoma (continued). "Furthermore, the increase in caspase-2 upon TRIM25 knockdown was only observed on the protein level but not on the mRNA level, independent of the colon carcinoma cell line that was assessed." (PMID 31842382, 2019).
colorectal cancer (16 papers, 2017 to 2026). A primary or metastatic malignant neoplasm that affects the colon or rectum. "However, exposure of human colorectal carcinoma cells HCT-116 to proanthocyanidins from the same source significantly upregulated mRNAs encoding caspase-2, caspase-3 and caspase-9." (PMID 31752295, 2019). "In most studies, cysteine-aspartate specific protease 2 (CASP2) is under-expressed in colorectal cancer tissues, and its downregulation is believed to facilitate tumor cell evasion of apoptosis." (PMID 41614944, 2026). "On the contrary, cleavage of caspase-2 and up-regulated expression of Bim, a pro-apoptotic Bcl-2 family protein, was induced by the overexpression of miR-210 in colorectal cancer, resulting in apoptotic cell death." (PMID 36171196, 2022). "We have previously demonstrated that FC induces apoptosis in human colorectal cancer HT-29 cells via mitochondrion- and caspase 2-related pathways." (PMID 35204181, 2022). "Considering that caspase-2 is involved in both intrinsic and extrinsic apoptotic pathways and can be activated by miR-210 overexpression in colorectal cancer, indicates that a more complex role of the miR-210/caspase-2 axis exists in disease development." (PMID 36171196, 2022). "This repression of caspase-2 resulted in increased aneuploidy in colorectal cancer cell lines, thought to exacerbate genetic variability and drug resistance in tumors." (PMID 33425918, 2020). "In support of this function, it was shown that when caspase-2 expression is suppressed in a model of colorectal cancer, aneuploidy increased." (PMID 33425918, 2020). "Together, our study implicates that TRIM25-dependent inhibition of caspase-2 may represent a so far unrecognized survival mechanism of colorectal carcinoma cells." (PMID 31842382, 2019). "However, p62 might act as a tumor suppressor in esophageal adenocarcinoma and colorectal cancer under certain circumstances, indicating that an increased level of p62, leading to caspase-2 activation, could improve the prognosis of several tumor types." (PMID 39543123, 2024). "Thus, targeting the constitutive binding of HuR to caspase-2 mRNA may represent a promising therapeutic approach for sensitizing colorectal carcinoma cells to currently used anti-tumor therapies." (PMID 31366165, 2019). "Functionally, the herein described TRIM25-dependent inhibition of caspase-2 could represent a so far unrecognized post-transcriptional survival mechanism utilized by colorectal carcinoma cells, and further supports the tumorigenic capacity of this particular TRIM member." (PMID 31842382, 2019). "In the commonly used mouse tumor cells, like CT26 (colorectal carcinoma) and MC38 (colon adenocarcinoma), endogenous caspase-2 expression was modest, comparable to that in human Jurkat cells." (PMID 38676703, 2024). "Using a colorectal cancer cell line, this group demonstrated that BCL9L represses caspase-2 at the transcriptional level, resulting in lower protein levels." (PMID 33425918, 2020).
colorectal cancer (continued). "An RNA-specific binding of TRIM25 to caspase-2 mRNA in DLD-1 cells was validated by the RNP-IP RT-PCR assay and confirmed in the colorectal cancer cell line RKO." (PMID 31842382, 2019). "Furthermore, our data implicate that inhibition of caspase-2 by TRIM25 protects tumor cells from chemotherapeutic drug-induced apoptosis and may constitute a novel mechanism of drug resistance in human colorectal carcinoma cells." (PMID 31842382, 2019).
neuroblastoma (16 papers, 2012 to 2025). Neuroblastoma (NB) is the most common solid, extracranial childhood tumor. "To exclude potential cleavage of caspase-2 by caspase-8, which can undergo p62-mediated activation, we used SK-N-BE cells, a neuroblastoma cell line characterized by loss of caspase-8 expression." (PMID 39543123, 2024). "Loss of caspase-2 inconsistently delayed tumorigenesis in a MYCN mouse model of neuroblastoma (TH-MYCN), in which MYCN was constitutively expressed under the control of the rat tyrosine hydroxylase promoter." (PMID 34069817, 2021). "In particular, our findings indicating that loss of Casp2 impacts neuronal differentiation, is likely a key contributor to delaying neuroblastoma onset and reduced adrenal tumor development in Th-MYCN/Casp2−/− mice." (PMID 30670683, 2019). "In particular, while caspase-2 deficiency augments lymphoma development in the EμMyc mouse model, it leads to delayed neuroblastoma development in Th-MYCN mice." (PMID 30670683, 2019). "This indicates that Casp2 loss can affect neuronal differentiation and gene transcription in neuroblastoma." (PMID 30670683, 2019). "To identify genes associated with delayed neuroblastoma development in Th-MYCN/Casp2−/− mice, we examined various molecular biomarkers of neuroblastoma development and prognosis." (PMID 30670683, 2019). "Considering that diploidy is strongly associated with unfavorable prognosis of neuroblastomas, the increased aneuploidy caused by low levels of caspase-2 expression may be causally related to increased patient survival." (PMID 34069817, 2021). "Further elucidation of the caspase-2-associated pathway and its substrates may provide a new strategy of molecular targeted therapy in neuroblastomas." (PMID 34069817, 2021). "Although several studies employing mouse models of tumorigenesis support a tumor suppressor role for caspase-2, cancer-promoting role for caspase-2 has been reported for MYCN-driven neuroblastoma in a mouse model." (PMID 38429264, 2024). "Collectively, these data suggest that CASP2 is essential for HSV‐2‐induced GSDME‐dependent pyroptosis in human SH‐SY5Y neuroblastoma cells." (PMID 37646198, 2023). "In a model of ThMycn-induced neuroblastoma, Th-Mycn/Casp2 null mice had delayed onset of tumor formation, suggesting that caspase-2 potentiated tumor growth in this model." (PMID 33425918, 2020). "Upon its discovery, it was shown that overexpression of caspase-2 resulted in apoptotic cell death in fibroblasts and neuroblastoma cells." (PMID 33425918, 2020). "Identification of caspase-2 substrate(s) and/or interacting partners in differentiating NCCs will be key to defining its role in neurons and elucidate its function in neuroblastoma." (PMID 30670683, 2019). "Here, we also found that higher Megf6 transcript levels are associated with poor outcome in this neuroblastoma subset, and this is consistent with our RNA-seq data and the delayed tumorigenesis observed in the Th-MYCN/Casp2−/− mouse model." (PMID 30670683, 2019). "RABV infection has been reported to induce autophagy during viral replication in human and mouse neuroblastoma cell lines, via downregulating the CASP2/caspase 2 pathway or by activating AMPK–AKT–mTOR and AMPK–MAPK pathways." (PMID 29673174, 2018). "We have previously performed cDNA microarray analysis and found that TRIM16 overexpression resulted in an increase in caspase-2 expression in neuroblastoma cancer cells." (PMID 23404198, 2013). "Mechanistic understanding of caspase-2-dependent cell death pathways is gradually improving and may provide an insight into newly targeted drugs in neuroblastomas, introduced in the next section." (PMID 34069817, 2021). "Moreover, human neuroblastoma samples showed a correlation between low levels of caspase-2 expression and increased patient survival in the subset of MYCN-non-amplified neuroblastomas." (PMID 34069817, 2021).
neuroblastoma (continued). "Nevertheless, the finding here, show that loss of Casp2 affects several components regulating the Wnt signaling pathway in neuroblastoma, that could impact neuronal differentiation and possibly neuroblastoma onset in Th-MYCN/Casp2−/− mice." (PMID 30670683, 2019). "Together, these data identify altered expression levels of several Wnt-associated genes and suggest a fine-tuning of Wnt signaling components in Th-MYCN/Casp2−/− tumors that may determine neural crest cell (NCC) specification to influence neuroblastoma onset." (PMID 30670683, 2019). "The delayed neuroblastoma onset in Th-MYCN/Casp2−/− mice, previously highlighted the tissue/context specific role for caspase-2 in tumor suppression." (PMID 30670683, 2019). "Both caspase-9 and caspase-2 are well established initiator caspases for intrinsic apoptotic pathway suggesting for the first time that, MPTQ treated neuroblastoma cell death is mediated through only caspase-9 driven intrinsic apoptotic pathway." (PMID 23824039, 2013). "Overall, we found that downregulation of 7 genes (Crb1, Lrrc9, Rcn1, Rtl1, Shisa3, Six6, St18) and upregulation of 2 genes (C1ql3, Slc18A1), are strongly predictive of favorable neuroblastoma outcome, consistent with delayed tumor development in Th-MYCN/Casp2−/− mice." (PMID 30670683, 2019). "In this report, we observed consistent activation of caspase-9 in the form of a ∼35 kDa protein (cleaved caspase-9) but not caspase-2 in MPTQ treated neuroblastoma cells." (PMID 23824039, 2013). "However, the absence of caspase-2 is not sufficient to promote tumorigenesis in the MYCN-driven neuroblastoma model or following 3-methylcholanthrene (3-MC)-induced fibrosarcoma and irradiation-driven lymphoma." (PMID 38429264, 2024). "In summary, essential functions of caspase-2, in not only pro-apoptotic but also non-apoptotic functions (including cell cycle arrest for maintaining genome integrity), have provided some possible links to neuroblastoma tumorigenesis." (PMID 34069817, 2021). "This indicates that this process is not CASP2-mediated, implying that the role of BIRC6 in neuroblastoma is not essential for completion of cell division during midbody ring formation." (PMID 22788920, 2012).